GACAT3 (gastric cancer associated transcript 3)
Synonyms: lncRNA-AC130710; LINC01458
Gene: Long non-coding RNA gene on chromosome 2 (16,013,928 to 16,087,201, forward strand). Ensembl gene ENSG00000236289.
Diseases named in the same sentence as GACAT3 in open-access papers:
GACAT3 is named in the same sentence as 15 diseases in open-access papers, as found by Europe PMC text mining. Sharing a sentence is not in itself a finding about the gene and the disease. The quoted sentences say what the papers report.
gastric cancer (10 papers, 2016 to 2024). A primary or metastatic malignant neoplasm involving the stomach. "In addition, CuB regulates the expression of the lncRNA gastric cancer-associated transcript 3, which induces apoptosis in gastric cancer cells." (PMID 34295808, 2021). "GACAT3 was closely associated with gastric cancer in previous studies." (PMID 32587825, 2020). "In GC, lncRNA gastric cancer-associated transcript 3 (GACAT3) works as a downstream target of IL6/STAT3 signaling pathway to accomplish its function." (PMID 29736267, 2018). "More recently, GACAT3 was reported to be abnormally expressed in many malignant tumors, including gastric cancer, hepatocellular carcinoma, colorectal cancer, breast cancer, bladder cancer, glioma, ovarian cancer, and non-small cell lung cancer." (PMID 35127682, 2022). "Many studies show that GACAT3 is dysregulated in cancers, such as gastric cancer, colorectal cancer, hepatocellular carcinoma, breast cancer, bladder cancer, and glioma." (PMID 35127682, 2022). "GACAT3 is the first to be found to significantly overexpress in gastric cancer tissues and gastric cancer cell line MGC-803." (PMID 33520012, 2020). "By reviewing literatures, only one of eight prognostic lncRNAs, GACAT3, has been reported to play crucial roles in the gastric carcinoma." (PMID 27074572, 2016). "lncRNA GACAT3, as a competitive endogenous RNA of HMGA1, can alleviate cucurbitacin B-induced apoptosis in gastric cancer cells." (PMID 35082972, 2022). "In follow-up cell line experiments, significantly higher expression of GACAT3 was observed in MGC-803 cells compared to the normal gastric GES-1 cell line, whereas GACAT3 was expressed at remarkably lower levels in BGC-823, SGC-7901, and AGS gastric cancer cells compared to GES-1 cells." (PMID 35127682, 2022).
glioma (10 papers, 2019 to 2024). A benign or malignant brain and spinal cord tumor that arises from glial cells (astrocytes, oligodendrocytes, ependymal cells). "LncRNA gastric cancer associated transcript 3 (GACAT3), is greatly involved in apoptosis regulation and development of various cancers including cancers of breast, colorectal, bladder, glioma and more importantly gastric." (PMID 39075259, 2024). "GACAT3 has also been confirmed as a diagnostic biomarker in glioma and is predictive of progression in breast cancer." (PMID 35127682, 2022). "Interestingly, this miRNA is sponged by LncRNA gastric cancer-associated transcript 3 (GACAT3), which is upregulated in glioma tissues from patients and thus promotes HuR overexpression." (PMID 35884580, 2022). "Similarly, in gliomas, gastric cancer-associated transcript 3 (GACAT3), another long non-coding RNA, regulates NAMPT expression and promotes glioma progression by acting as a molecular sponge to miR-135a, inhibiting its interaction with its target, NAMPT." (PMID 34068917, 2021). "In glioma, GACAT3 targets miR-3127-5p to downregulate ELAVL1 expression, thereby significantly enhancing cell proliferation and colony formation of A172 cells, U251 cells, and xenograft tumors." (PMID 35127682, 2022). "GACAT3 expression is also substantially higher in the glioma cell lines U87, U251, and A172 compared to the normal brain cell line HA 1800." (PMID 35127682, 2022). "Experimental evidence suggests that GACAT3 functions as an oncogene by regulating proliferation, apoptosis, migration, and invasion in glioma cells." (PMID 35127682, 2022). "In glioma, both in vitro and in vivo studies demonstrate that GACAT3 inhibits apoptosis by attenuating miR-3127-5p and consequently elevating ELAVL1 levels." (PMID 35127682, 2022). "Another long-stranded non-coding RNA, gastric cancer-associated transcript 3 (GACAT3), promotes the development of gliomas by functioning as a molecular sponge for miR-135a, blocking its interaction with NAMPT, and controlling NAMPT production." (PMID 36160449, 2022). "Recent studies have shown that GACAT3 is overexpressed in glioma tissues and is incrementally elevated during disease progression." (PMID 35127682, 2022). "In glioma, GACAT3 substantially upregulates NAMPT expression, which enhances cell migration and invasion via sponging miR-135a in U87 and U251 cells." (PMID 35127682, 2022). "GACAT3 was recently demonstrated to promote progression of colorectal cancer, breast cancer, and glioma." (PMID 32587825, 2020). "A finding has demonstrated that lncRNA GACAT3 performs as a molecular sponge for miR‐135a in glioma." (PMID 31827400, 2019). "GACAT3 has also been implicated in the prognosis of CRC, glioma, and NSCLC." (PMID 35127682, 2022). "Moreover, GACAT3 also mediates glioma cell proliferation by regulating NAMPT via competitive binding to miR-135a." (PMID 35127682, 2022). "Subsequently, further studies have demonstrated that GACAT3 acts as an oncogenic lncRNA and contributes to the development of various cancers, including breast cancer, colorectal cancer, bladder cancer, and glioma." (PMID 34496842, 2021). "Moreover, GACAT3 was also found to similar tumorigenesis in breast cancer, glioma, and colorectal cancer." (PMID 33520012, 2020). "Specifically, GACAT3 is considered to be a valuable target for therapeutic intervention in GC, CRC, HCC, breast cancer, bladder cancer, NSCLC, and glioma." (PMID 35127682, 2022). "Emerging evidence demonstrates that GACAT3 is remarkably upregulated in CRC, HCC, breast cancer, NSCLC, bladder cancer, and glioma but shows diverse expression in GC cell lines." (PMID 35127682, 2022). "GACAT3 is aberrantly expressed in GC, CRC, HCC, breast cancer, bladder cancer, and glioma." (PMID 35127682, 2022).
breast carcinoma (7 papers, 2020 to 2023). "GACAT3, gastric cancer associated transcript 3 is a long non-coding RNA that has been previously implicated in gastric and other cancers, with high expression observed in breast cancer tissue and correlated with prognosis among breast cancer patients." (PMID 37345113, 2023). "Some lncRNAs were considered to be beneficial prognostic indicators to predict prognosis in breast cancer; for instance, lncRNA GACAT3 predicted poor prognosis, and lncRNA H19 was associated with poor prognosis and promoted cancer stemness." (PMID 32967061, 2020). "Similarly, GACAT3 is associated with reduced OS and poor prognosis in breast cancer." (PMID 35127682, 2022). "Studies have observed higher GACAT3 expression in breast cancer tissues and MCF-7 cells compared to adjacent normal tissues and the normal breast epithelial MCF-10A cell line." (PMID 35127682, 2022). "In breast cancer, GACAT3 promotes cell apoptosis by downregulating caspases 3 and 9 as well as by upregulating BAX and Bcl-2 via miR-497 in MCF-7 cells." (PMID 35127682, 2022). "Downregulation of GACAT3 significantly inhibits proliferation, migration, and invasion of breast cancer cells." (PMID 35127682, 2022). "In breast cancer, GACAT3 promotes cell proliferation by reducing the levels of caspase 9 and upregulating the expression of Bcl-2 in MCF-7 cells." (PMID 35127682, 2022). "However, some genes in previous studies are inconsistent with our study; for instance, upregulated lncRNA GACAT3 in breast cancer enhances its endogenous target CCND2 through sponging miR-497, which was found to be correlated with a poor prognosis." (PMID 35846145, 2022). "Moreover, GACAT3 is associated with CA19-9 levels in HCC and poor MRI diffusion weighted imaging in breast cancer, which are both indicative of aggressive tumors." (PMID 35127682, 2022). "In breast cancer, wounding healing assays in MCF-7 cells show that GACAT3 knockdown dramatically decreases cell migration." (PMID 35127682, 2022).
hepatocellular carcinoma (3 papers, 2019 to 2022). A malignant tumor that arises from hepatocytes. "Studies in tissues and cell lines agree that inhibition of GACAT3 suppresses the ability of hepatoma cells to proliferate and migrate and promotes cell apoptosis." (PMID 35127682, 2022).
bladder cancer (2 papers, 2020 to 2022). "High level expression of GACAT3 was associated with high grade and stage bladder cancer." (PMID 33537343, 2020). "The differential expression patterns of GACAT3 between bladder cancer and control and the association of GACAT3 with clinicopathological features suggest that long non-coding RNA GACAT3 emerges as a novel player in the development and progression of the bladder cancer." (PMID 33537343, 2020). "GACAT3 is upregulated in bladder cancer tissues, and elevated GACAT3 expression positively correlates with advanced bladder cancer grade and stage." (PMID 35127682, 2022). "In CRISPR-Cas13-transfected bladder cancer T24 and 5637 cell lines, GACAT3 promotes cell proliferation, suppresses apoptosis, and enhances cell migration by downregulating p21, BAX, and E-Cadherin protein levels, respectively." (PMID 35127682, 2022). "The results demonstrated that GACAT3 was up-regulated in bladder cancer tissues than that in the paired normal tissues." (PMID 33537343, 2020). "Since GACAT3 displayed striking oncogenic activity in previous studies, it is intriguing to explore its biological function in bladder cancer." (PMID 33537343, 2020). "Induced cell apoptosis and suppressed cell migration were observed in both bladder cancer cell lines after knockdown of GACAT3." (PMID 33537343, 2020). "More works will be needed to determine the potential molecular mechanism of GACAT3 in the regulation of Bax and E-cadherin in bladder cancer." (PMID 33537343, 2020). "The relative expression level of GACAT3 was detected by utilizing the Real-Time qPCR in a total of 32 patients with bladder cancer." (PMID 33537343, 2020). "GACAT3 was upregulation in bladder cancer compared to the paired normal tissues." (PMID 33537343, 2020). "To understand the possible impacts of GACAT3 on bladder cancer, we determined the changes in cell proliferation, apoptosis and motility induced by knockdown of GACAT3 in bladder cancer by using CRISPR-Cas13 biotechnology, which has a better targeting performance than that of siRNA/shRNA." (PMID 33537343, 2020). "Moreover, we also found that GACAT3 can inhibit cell apoptosis, and promote cell proliferation and migration by downregulating the expression of P21, Bax, and E-cadherin proteins in bladder cancer." (PMID 33537343, 2020). "By using CRISPR-Cas13 biotechnology, we suggested that GACAT3 may be a novel target for diagnosis and treatment of bladder cancer." (PMID 33537343, 2020). "Targeting GACAT3 may be a promising approach to the treatment of bladder cancer." (PMID 33537343, 2020). "With this aim, in this study, we found that GACAT3 was overexpressed in bladder cancer compared to matched normal tissue." (PMID 33537343, 2020). "Bladder cancer T24 and 5637 cell lines were transfected with GACAT3 related CRISPR-Cas13 or negative control CRISPR-Cas13." (PMID 33537343, 2020).
esophageal squamous cell carcinoma (1 paper, 2021). Esophageal squamous cell carcinoma (ESCC) is a type of esophageal carcinoma (EC) that can affect any part of the esophagus, but is usually located in the upper or middle third. "However, GACAT3’s levels and role in esophageal squamous cell carcinoma (ESCC) has not been elucidated." (PMID 34496842, 2021).
liver cancer (1 paper, 2022). An epithelial or non-epithelial malignant neoplasm that arises from the liver. "Specifically, N-cadherin, β-catenin, and TGF-β1 levels are reduced, and E-cadherin levels are elevated, demonstrating that GACAT3 has important implications for cell migration and invasion in liver cancer." (PMID 35127682, 2022). "In liver cancer cell lines, reduced expression of BAX and elevated expression of Bcl-2 (anti-apoptotic) support the anti-apoptotic effect of GACAT3." (PMID 35127682, 2022). "GACAT3 is aberrantly overexpressed in HCC tissues and liver cancer cell lines, including HepG2, HCCLM3, SK-Hep-1, SMMC-7721, and Huh7." (PMID 35127682, 2022). "In liver cancer, the expression of EMT factors is altered following suppression of GACAT3 in HepG2 and HCCLM3 cell lines." (PMID 35127682, 2022).
lung carcinoma (1 paper, 2020). "Overexpression of GACAT3 in lung cancer cells promoted cell proliferation and migration, and it enhanced their sensitivity to radiotherapy." (PMID 32587825, 2020).
lymph node metastasis (1 paper, 2022). "Clinicopathologic analyses indicate that GACAT3 overexpression is significantly associated with lymph node metastasis and TNM stage but is not correlated with age, gender, or smoking history." (PMID 35127682, 2022). "Clinicopathological analyses of CRC suggest that GACAT3 is positively related to tumor infiltration depth, TNM stage, lymph node metastasis, and CA19-9 level." (PMID 35127682, 2022).
ovarian carcinoma (1 paper, 2022). A malignant neoplasm originating from the surface ovarian epithelium. "Moreover, GACAT3 is included in an established ovarian cancer eight-lncRNA signature, which predicts chemotherapy response and platinum-resistance." (PMID 35127682, 2022).
cancer (8 papers, 2020 to 2024). A tumor composed of atypical neoplastic, often pleomorphic cells that invade other tissues. "Abnormal expression of GACAT3 in specific cancer tissues can reliably differentiate normal tissue from diseased tissue, suggesting that GACAT3 is a useful diagnostic biomarker in these cancers." (PMID 35127682, 2022). "Here, we review GACAT3 expression in human cancers, the association of GACAT3 with clinical characteristics, and the biological functions and regulatory mechanisms of GACAT3 in tumorigenesis." (PMID 35127682, 2022). "GACAT3 expression and association with clinicopathological features of human cancers." (PMID 35127682, 2022). "Additional in-depth exploration of GACAT3 mechanisms are necessary to design effective cancer therapies." (PMID 35127682, 2022). "In summary, although GACAT3 expression varies among GC cancer cell lines, the overwhelming majority of evidence suggests that GACAT3 functions as an oncogene in GC." (PMID 35127682, 2022). "In this review, we integrate the current understanding of the pathological features, biological functions, and molecular mechanisms of GACAT3 in cancer." (PMID 35127682, 2022). "In general, GACAT3 promotes the survival of malignant cells by impairing apoptosis and is a promising target to sensitive malignant cells to anti-cancer therapies." (PMID 35127682, 2022). "Accumulating evidence demonstrates that GACAT3 participates in the tumorigenesis of multiple human cancers." (PMID 35127682, 2022). "The molecular function of GACAT3 is well-established and suggests that GACAT3 is a promising prognostic marker and target for therapy in specific cancers." (PMID 35127682, 2022). "The lncRNA gastric cancer-associated transcript 3 (GACAT3, also known as AC130710) is one such example of a cancer-associated lncRNA." (PMID 35127682, 2022). "Specific GACAT3-targeted drug therapy offers a new direction and hope for cancer treatment." (PMID 35127682, 2022). "Thus, GACAT3 is a potential tumor biomarker for cancer diagnosis, prognosis, and targeted therapy." (PMID 35127682, 2022). "Among the 15 RFS-related lncRNAs, AP002478.1, GACAT3, and LINC00462 have been previously reported to be related to cancers." (PMID 33520012, 2020).
tumor (6 papers, 2019 to 2025). "Despite these opposing results in cell lines, high GACAT3 expression in GC tissues is positively associated with tumor size, tumor-node-metastasis (TNM) stage, and distal metastasis." (PMID 35127682, 2022). "GACAT3 has been implicated in these three processes as well as in tumor growth, apoptosis, metastasis, epithelial-mesenchymal transition (EMT), and drug resistance." (PMID 35127682, 2022). "The higher expression of GACAT3 significantly was associated with tumor size, distant metastasis, TNM stages, and shorter OS." (PMID 33520012, 2020). "GACAT3 plays an important role in cell-cycle progression and was associated with aggressive tumor behavior." (PMID 33537343, 2020). "Notably, a study that employed breast MRI and diffusion-weighted imaging found that elevated expression of GACAT3 was associated with reduced perfusion-related diffusion and increased perfusion fraction, which are indicative of aggressive tumor biology and undesirable chemotherapy effects." (PMID 35127682, 2022). "Knockdown of GACAT3 and overexpression of its relevant miRNA networks suppresses tumor progression, suggesting GACAT3 is a potential therapeutic target." (PMID 35127682, 2022). "Functional analyses from several tumor types suggest that GACAT3 promotes cell proliferation and tumor growth by interacting with a variety of miRNAs and signaling pathways." (PMID 35127682, 2022). "Overexpression of GACAT3 correlates with clinicopathological features, including tumor size, tumor grade, stage of development, and lymph node metastasis." (PMID 35127682, 2022). "We discuss the importance of the relationship between GACAT3 and tumor cell proliferation, apoptosis, migration, and invasion below." (PMID 35127682, 2022). "In NSCLC, GACAT3 plays a positive role in tumor growth and cell proliferation by directly targeting TIMP2 in xenografts and A549 cells." (PMID 35127682, 2022). "GACAT3 expression levels in tumor samples are generally correlated with tumor size, metastasis to lymph nodes, TNM stages, and patient survival." (PMID 35127682, 2022). "Real-time quantitative qPCR was used to detect the expression level of GACAT-3 in tumor tissues and paired normal tissues." (PMID 33537343, 2020). "Together, these observations suggest that GACAT3 distinguishes CRC from normal tissue and may also indicate tumor stage, supporting the development of GACAT3 as a biomarker in CRC." (PMID 35127682, 2022). "Furthermore, in vitro and in vivo experiments reveal that GACAT3 enhances cellular proliferation, migration, invasion, and tumor growth, which all contribute to aggressive tumor progression." (PMID 35127682, 2022). "A literature search revealed that FOXM1 is a miR-149 target, indicating that FOXM1 might contribute to the tumor-inducing function of GACAT3." (PMID 34496842, 2021). "Next, xenograft assays demonstrated GACAT3 knockdown reduced ESCC tumor growth in nude mice." (PMID 34496842, 2021). "In addition, tumor samples from the GACAT3 knockdown group showed decreased GACAT3 and increased miR-149 amounts." (PMID 34496842, 2021). "In addition, colony formation and invasion assays verified that GACAT3 promotes ESCC tumor progression through miR-149." (PMID 34496842, 2021). "For instance, GACAT3, generally associated with elevated expression in breast cancer tissues, was hypermethylated despite its usual upregulation in malignancies, whereas DELEC1, a known tumor suppressor, exhibited hypermethylation correlating with reduced gene activity." (PMID 40566344, 2025). "LncRNAs such as GACAT3, DELEC1, CASC2, and LCIIAR exhibited altered methylation status under PFOS exposure, suggesting potential disruption of tumor-suppressive functions or promotion of malignant phenotypes." (PMID 40566344, 2025). "Functional studies showed that GACAT3 silencing reduced the proliferation, migration and invasion of cultured ESCC cells, and decreased tumor growth in mice." (PMID 34496842, 2021).
tumor (continued). "Although GACAT3 does not promote malignant cell proliferation via one consistent pathway or interaction, it does appear to influence proliferation via its ceRNA function in multiple tumor types, which may represent a therapeutic vulnerability." (PMID 35127682, 2022).
GACAT3 also shares sentences with these, for which no sentence is quoted: colorectal cancer (3 papers); non-small cell lung carcinoma (1); renal cell carcinoma (1).